TMPRSS2 (transmembrane serine protease 2)
Diseases named in the same sentence as TMPRSS2 in open-access papers (continued):
Sharing a sentence is not in itself a finding about the gene and the disease.
COVID-19 (continued). "Based on the androgen effect on TMPRSS2 expression, numerous clinical trials are testing the ability of androgen deprivation therapies or anti-androgens to mitigate COVID-19." (PMID 34451827, 2021). "Another study found that essential SARS-CoV-2 receptors, such as ACE2 and TMPRSS2, are co-localized in adrenal cells, and that cortisol levels are lower in COVID-19-positive critically ill patients than in COVID-19-negative critically ill patients." (PMID 34299201, 2021). "The Spike protein requires proteolytic processing/priming by TMPRSS2 to mediate entry into lung cells; thus, small-molecule inhibitors of this target offer much promise as new therapeutics for COVID-19 and other coronavirus diseases." (PMID 34635581, 2021). "As such, we believe that agents identified here, that reduce TMPRSS2 expression, represent a rational approach to modify the clinical course of COVID-19, and potentially future related viral pandemics." (PMID 34162861, 2021). "However, specific variants of genes (e.g., ACE2, TMPRSS2, and interleukin-6 (IL-6)) or the differential expression of related genes may explain the individual differences in the sensitivity and severity of COVID-19 by altering the kinetics of the viral interaction and endocytosis." (PMID 33404925, 2021). "Regarding more specifically COVID-19, H2S inhibits transmembrane protease serine 2 (TMPRSS2), a protease that promote ACE2 proteolytic cleavage using different targets in the protein sequence and amplifies SARS-CoV-2-entry via the endocytic pathway." (PMID 34448938, 2021). "Altogether, available evidence points toward two not-mutually exclusive mechanisms in gender susceptibility to COVID-19 by sex hormonal regulation of ACE2 and TMPRSS2." (PMID 32936429, 2021). "While ACE2 expression increased in females either due to skewed chromosome X inactivation or by estrogens, reduced androgen levels in women resulted in low TMPRSS2 expression increasing its protective role against COVID-19 development and progression." (PMID 33777332, 2021). "Altogether, available evidence points toward two not-mutually exclusive mechanisms in differential gender susceptibility to COVID-19 by sex hormonal regulation of the two main actors in SARS-CoV-2 infection: ACE2 and TMPRSS2." (PMID 32936429, 2021). "Research has suggested that cell entry of SARS-CoV-2, the virus that induces COVID-19, is associated with the ACE2 receptor and TMPRSS2." (PMID 33708781, 2021). "RNA-seq data show that NRP1 level is slightly decreased in peripheral blood of ICU admitted COVID-19 patients, unaltered in lung, while TMPRSS2 level is significantly decreased in lung of COVID-19 patients." (PMID 34168096, 2021). "SARS-CoV-2, the causative agent of COVID-19, infects host cells using the angiotensin I converting enzyme 2 (ACE2) as its receptor after priming by host proteases, including TMPRSS2." (PMID 33922918, 2021). "Concurrent studies on the physiological role of TMPRSS2 in humans will produce better evidence in favour of the application of protease inhibitors for COVID-19." (PMID 34336361, 2021). "Thereby, TMPRSS2 inhibitors such as bromhexine, aprotinin, camostat, and nafamostat are useful in managing COVID-19 through attenuation of TMPRSS2-dependent lung inflammation, coagulopathy, and development of ARDS." (PMID 34568081, 2021). "COVID-19 is a viral disease with respiratory failure caused by SARS-CoV-2 entering cells through host ACE2 and TMPRSS2." (PMID 33706759, 2021). "It was thought that since older men tended to have more severe symptoms of COVID-19, it was plausible that increased TMPRSS2 expression was involved in the disparity." (PMID 34574709, 2021). "Regarding COVID-19, epigenetics, specific variants, ACE2 and TMPRSS2 polymorphisms, ethnicity, as well as inborn immunity errors, have been reported worldwide." (PMID 34016042, 2021). "There are several clinical trials ongoing exploring ADT and TMPRSS2 blockers (Camostat and Nafamostat) in the treatment of COVID-19." (PMID 34823563, 2021).
COVID-19 (continued). "This epidemiological evidence strengthens the usefulness of TMPRSS2 inhibitors for COVID-19 management." (PMID 34201505, 2021). "Entry into lung cells of the SARS-CoV-2 virus, responsible for COVID-19, is facilitated by host proteins TMPRSS2 and ACE-2, expressed on the surface of lung cells." (PMID 34328182, 2021). "Due to the roles in SARS-CoV-2 infection, ACE2, NRP1 and TMPRSS2 are targets for drug design for COVID-19." (PMID 34168096, 2021). "A different protease inhibitor, namely camostat mesylate, has recently been reported as an anti-COVID-19 agent in humans and exerts its effect by inhibiting transmembrane protease serine 2 (TMPRSS2)-dependent viral entry into the host cell." (PMID 33495684, 2021). "The enhanced susceptibility of obese individuals to severe COVID-19 outcomes has been linked to elevations in ACE2 and TMPRSS2 in lung tissues." (PMID 34684358, 2021). "It was observed that severity of COVID-19 is associated with the polymorphisms of ACE2 and TMPRSS2 expressing genes." (PMID 34336361, 2021). "While previous efforts have demonstrated the role of ACE2 and TMPRSS2 in host defense against COVID-194, there remains limited understanding for the role of host genetics contributing to severe COVID-19 outcome variability." (PMID 34315903, 2021). "Next, to investigate the localization of SARS-CoV-2 in the human kidney, SARS-CoV-2 nucleoprotein was co-stained with ACE2 or TMPRSS2 by Immunofluorescence (IFC) staining in 10 COVID-19-infected kidney samples, respectively." (PMID 34136484, 2021). "Further studies are needed to show a direct correlation between ACE2 and TMPRSS2 expressions in cancer patients and the incidence and severity of COVID-19." (PMID 34442770, 2021). "On the other hand, androgens seem to play a pivotal role in COVID-19 by promoting the transcription of the transmembrane protease, serine 2 (TMPRSS2) gene." (PMID 32661947, 2021). "Camostat and Nafamostat were demonstrated to be effective TMPRSS2 inhibitors and are in clinical trials for COVID-19 treatment (ClinicalTrials.gov (accessed on 28 March 2021) Identifier: NCT04321096 for Camostat and NCT04352400 for Nafamostat)." (PMID 34209110, 2021). "This is the first case-control study analyzing the role of TMPRSS2 rs2070788 with regard to COVID-19." (PMID 33968142, 2021). "S protein activation depends on both furin and TMPRSS2, which holds a promising target strategy for clinical management of COVID-19." (PMID 34869231, 2021). "One of the risk factors for acquiring COVID-19 is the level of expression of SARS-CoV-2 entry receptors, ACE2 and TMPRSS2, in lung tissue." (PMID 35111161, 2021). "The greater dependence of SARS-CoV-2 on TMPRSS2 has an immediate implication for the treatment of COVID-19." (PMID 33465165, 2021). "In contrast, the low expression of intestinal ACE2 (p = 0.00264) or TMPRSS2 (p = 0.00295) was correlated with a high level of COVID-19 death in men, which is seemingly related to age." (PMID 34832534, 2021). "The TMPRSS2 gene is transcribed and regulated by the androgen receptor, and the main target of TMPRSS2 expression in COVID-19 is the lungs, kidneys, and liver." (PMID 34484179, 2021). "The relatively high expression of those proteases in cardiac tissue, as observed in our model of PCOS, would provide an alternative route for SAR-CoV-2 for cell infection bypassing Tmprss2 and help explain cardiac pathology in COVID-19." (PMID 33922918, 2021). "Little is known of the patterns of expression of ACE2 and TMPRSS2 or the clinical characteristics of COVID-19 in patients with COVID-19 and colorectal cancer." (PMID 33479506, 2021). "Lower levels of angiotensin-converting enzyme 2 (ACE2) and transmembrane serine protease 2 (TMPRSS2) in the nasal epithelium of children may be related to a lower incidence of severe acute respiratory syndrome coronavirus 2 (SARS-CoV-2) infection, compared to adults." (PMID 34730438, 2021).
COVID-19 (continued). "Uncertain results emerge from the comparison of both ACE2 and TMPRSS2 expression and functional activities between COVID-19-positive subjects and cancer patients." (PMID 34716309, 2021). "Single-cell RNA sequencing (scRNA-Seq) has demonstrated that both ACE2 and TMPRSS2 are co-expressed in multiple tissues affected by COVID-19, including airway epithelial cells, cornea, digestive and urogenital systems." (PMID 34820418, 2021). "The presence of several MASPs capable of priming the spike proteins of SARS-CoV-2 virions, in synergy with or in place of TMPRSS2, offers straightforward explanations for clinical data on COVID-19 that remain unresolved to date." (PMID 33268377, 2021). "Collectively, the computational data supported these drugs as potential TMPRSS2 inhibitors for treating COVID-19." (PMID 34209110, 2021). "Antimalarial drugs CQ and HCQ (hydroxychloroquine) exert strong anti-SARS-CoV-2 effects in SARS-CoV-2 infected Vero E6 cells but fail to inhibit SARS-CoV-2 replication in TMPRSS2-expressing human lung cells or animal models and COVID-19 patients." (PMID 34960736, 2021). "The expression and function of the steroid hormone receptor family is important in many aspects that impact on COVID-19 effects in the lung – notably lung development and function, the immune system, and expression of TMPRSS2 and ACE2." (PMID 34328182, 2021). "With this background, we searched for possible genetic components of COVID-19 severity among Italians by looking at expression levels and genetic variants in ACE2 and TMPRSS2, two crucial genes for viral infection." (PMID 32501810, 2020). "Polyneuritis cranialis or convulsions in COVID-19 patients can reflect ENaC and TMPRSS2 malfunctions in trigeminal neurons." (PMID 33142989, 2020). "ACE2 and TMPRSS2 were shown to be the key mediators of SARS-CoV-2 viral entry early in the COVID-19 pandemic, but which cells of the upper airway tract express them and mechanisms governing their expression in the lung were not defined." (PMID 33310900, 2020). "Despite the early findings relating ACE2 and TMPRSS2 to COVID-19, a link between SARS-CoV-2 infection outcome and other proteases such as furin and cathepsin B/L is yet to be established." (PMID 33036180, 2020). "We focused on using single-cell-level ACE2 and TMPRSS2 expression data as a predictor, which has been validated to be meaningful at a certain degree by clinical data, showing that COVID-19 infects not only the lung but also other organs." (PMID 32973879, 2020). "Higher expression of ACE2 and TMPRSS2 in males, African Americans, and patients with diabetes mellitus provides rationale for monitoring these subgroups for high infectivity and poor COVID-19 outcomes." (PMID 33101356, 2020). "As a result, a drug that can interfere with ACE2 and/or TMPRSS2 interaction with the virus should, in fact, help in combating COVID-19." (PMID 33260592, 2020). "Since TMPRSS2 plays a very important role in SARS-CoV-2 cell entry and ACE2 dysfunction, blocking the activity of TMPRSS2 should be the primary strategy for preventing severe and critical conditions of COVID-19." (PMID 32354022, 2020). "The evidence presented in this review highlights the deleterious effect of ACE2 downmodulation by ADAM17 and TMPRSS2 in COVID-19 pathogenesis." (PMID 33117379, 2020). "Of note, whereas the role of ACE2 in endothelial function and in the pathogenesis of COVID-19 has been extensively investigated, the potential contribution of TMPRSS2 and its targeting as a novel therapeutic approach has been less studied." (PMID 33143053, 2020). "The trimeric COVID-19 S1 spike binds with the PD domain of ACE2 and cause cleavage of ACE2 C-terminal segment (residues 697–716) by the transmembrane protease serine 2 (TMPRSS2) enhances the S-protein-driven viral entry." (PMID 32974224, 2020).
COVID-19 (continued). "Collectively, we suggest that drugs predicted to have strong inhibitory potencies to ACE2 and TMPRSS2 through the DTI model should be considered as potential drug repurposing candidates for COVID-19." (PMID 33218024, 2020). "Both ACE2 and TMPRSS2 have been proposed as possible therapeutic targets for COVID-19, and clinical trials are underway for the TMPRSS2 inhibitors nafamostat and camostat mesylate." (PMID 33339864, 2020). "Among the SNPs of the TMPRSS2 gene, the rs2298659 SNP showed the strongest correlation (r2 = 0.7236, p = 0.0318) with the case fatality rate of COVID-19." (PMID 33396837, 2020). "Cellular mediators of COVID-19 and potential crosstalk with prostate cancer: Another factor connecting COVID-19 infection and prostate cancer is the high expression of TMPRSS2 in prostate cancer." (PMID 32641750, 2020). "The expression patterns of ACE2, AAK1, and TMPRSS2 were also evaluated in COVID-19 patients in GSE147507 to explore gene changes in the progression of the disease." (PMID 33195212, 2020). "Dozens of genes are co-expressed with ACE2 and TMPRSS2, many of which have plausible links to COVID-19 pathophysiology." (PMID 33318519, 2020). "TMPRSS2 is a serine protease strongly expressed in the prostate gland and is a promising camostat mesylate target for COVID-19 treatment." (PMID 32825469, 2020). "COVID-19 related inflammation, TMPRSS2, and prostate cancer: Recurrent gene arrangements are common in prostate cancer, and catastrophic chromosome rearrangements are a hallmark of prostate carcinogenesis." (PMID 32641750, 2020). "To further confirm the negative correlation between the level of TMPRSS2 transcript and microRNAs we assessed the expression of miR-503-5p and TMPRSS2 in an HNSCC patient positive to COVID-19." (PMID 32967703, 2020). "TMPRSS2 inhibitors including nafamostat and camostat are undergoing clinical trials to determine their efficacy against COVID-19." (PMID 32948238, 2020). "The protease inhibitors LPV/ R and CM, which have been most clinically studied on COVID-19, inhibit the activation of S protein by inhibiting the protease TMPRSS2." (PMID 34765999, 2020). "It is now regarded as a potential drug for curing COVID-19, since S protein driven viruses need TMPRSS2 to active S protein to ensure their entry, and CM can inhibit this process." (PMID 34765999, 2020). "This bears relationship to COVID-19, because TMPRSS2 expression is regulated by sex hormones, and COVID-19 shows predominance in males." (PMID 32719619, 2020). "Another factor that is suspected to be a deterministic one in the observed gender difference in COVID-19 transmission, severity, and mortality is the suspected differences in the expression of the TMPRSS2." (PMID 33117174, 2020). "Another promising TMPRSS2 inhibitor candidate for COVID-19 treatment is the broad range protease inhibitor camostat mesylate, which is approved for the treatment of pancreatitis." (PMID 32703818, 2020). "Presently, two ongoing clinical trials (NCT04321096 & NCT04338906) are testing the efficacy of TMPRSS2 inhibition by camostat mesilate to evaluate its benefits against COVID-19." (PMID 32645974, 2020). "Of note, a moderate expression of ACE2 and its co-expression with TMPRSS2 in the kidney/renal tissues also underlines association of SARS-CoV-2 infection with renal injury, which is frequently seen in COVID-19 patients." (PMID 32645974, 2020). "The present study demonstrates that TMPRSS2 and furin are promising drug targets for the treatment of COVID-19." (PMID 32703818, 2020). "We performed log-linear regression analysis between the case fatality rate of COVID-19 and allele frequencies of the polymorphisms of the IFITM3, ACE2, TMPRSS2, and IL6 genes in several ethnic groups." (PMID 33396837, 2020). "Additional in vitro and in vivo testing of the identified phytochemical inhibitors of TMPRSS2 and cathepsin L is needed before these molecules can enter clinical trials against COVID-19." (PMID 32842606, 2020).
COVID-19 (continued). "Cell entry of SARS-CoV-2, the novel coronavirus causing COVID-19, is facilitated by host cell angiotensin-converting enzyme 2 (ACE2) and transmembrane serine protease 2 (TMPRSS2)." (PMID 33318519, 2020). "The attempt to treat COVID-19 patients with recombinant ACE2 would likely be only partially effective in inhibition of cell-to-cell propagation mediated by TMPRSS2 and furin cleavage." (PMID 33142989, 2020). "Taken together, the drugs resulted through the MT-DTI affinity prediction for ACE2 and TMPRSS2 are suggested promising drug candidates for an effective drug repurposing strategy to treat COVID-19 in a target-wise perspective." (PMID 33218024, 2020). "Both deserve close attention as possible anti-COVID-19 drugs, owing to their confirmed effects on TMPRSS2 expression, as well the long history of their use, their known side effects, and their wide availability." (PMID 33375616, 2020). "Drugs that address ACE2, any sight of the RAAS, or TMPRSS2 expression are potential candidates for COVID-19." (PMID 32850920, 2020). "In spite of the higher expression levels of ACE2 and TMPRSS2 in neonates compared with adults, the clinical manifestations of pediatric COVID-19 cases were generally less severe." (PMID 33537060, 2020). "The rationale for their use is based on the blockage of conversion of testosterone into 5alplha-DHT and mitigation of TMPRSS2 expression, eventually hampering the overrepresentation of males, particularly bald ones, in severe COVID-19." (PMID 32993622, 2020). "The expression levels of TMPRSS2 and ACE2 were linked to the prognoses of COVID-19 patients." (PMID 40297833, 2025). "This is the first documented case suggesting a potential link between COVID-19-related prostatitis and subsequent prostate cancer in a TMPRSS2::ERG-altered patient without hereditary predisposition." (PMID 41267989, 2025). "COVID-19, caused by SARS-CoV-2, is a multisystem disease in which viral entry depends on angiotensin-converting enzyme 2 (ACE2) and transmembrane protease serine 2 (TMPRSS2)." (PMID 41267989, 2025). "TMPRSS2 expression, affected by sex hormones, could contribute to the more serious nature of COVID-19 in men; nevertheless, comparable expression indices in lung regions across genders imply that other variables most likely affect disease severity." (PMID 40297833, 2025). "Recent research revealed that AT III could inhibit the serine protease TMPRSS2, thereby decreasing viral load in COVID-19 patients and early SARS-CoV-2 infection." (PMID 40702576, 2025). "According to the results of the study, we found that the administration of the antiviral drug GS-5734 (remdesivir) and anti-inflammatory therapy reduces the level of TMPRSS2 in the blood, with the most significant changes observed in patients with moderate-severity COVID-19." (PMID 40573382, 2025). "Evaluation of ACE1, ACE2, and TMPRSS2 expression levels in COVID-19 outcomes." (PMID 39850833, 2025). "In conclusion, a multidisciplinary approach that includes molecular biology, pharmacology, immunology, and clinical research is required to fully understand TMPRSS2's varied role and aid the development of effective therapeutics for COVID-19 and other respiratory viral infections." (PMID 40297833, 2025). "Our findings do not support a strong relationship between ACE2 or TMPRSS2 expression levels and susceptibility to or severity of COVID-19." (PMID 40729397, 2025). "The TMPRSS2 protease has garnered significant attention in scientific literature due to its pivotal role as a host cell factor facilitating the viral entry and pathogenesis of SARS-CoV-2, the causative agent of COVID-19." (PMID 39858469, 2025). "The relative frequency of the SNP genes FGB (RS1800790), eNOS (RS2070744), TMPRSS2 (RS12329760) is not dependent on the severity of the COVID-19 clinical course and does not affect its risk." (PMID 40573382, 2025).